WNT9B (Wnt family member 9B)
Diseases named in the same sentence as WNT9B in open-access papers:
WNT9B is named in the same sentence as 44 diseases in open-access papers, as found by Europe PMC text mining. Sharing a sentence is not in itself a finding about the gene and the disease. The quoted sentences say what the papers report.
cleft lip (7 papers, 2015 to 2024). Congenital defect in the upper lip where the maxillary prominence fails to merge with the merged medial nasal prominences. "No coding mutations in Wnt9b has been reported in human while Wnt9b null mice develop incomplete penetrance of bilateral cleft lip." (PMID 39583201, 2024). "In previous studies, SHH signaling disturbances and loss of SHH function in the developing and growing lip epithelium have been associated with both UCL and BCL, while WNT9B functional disturbances have been associated with cleft lip and palate in mice." (PMID 37366674, 2023). "WNT9B gene mutations and dysfunction in mice have been associated with the development of orofacial clefts, such as cleft lip and cleft palate, by disrupting the WNT signaling pathways within the developing orofacial tissue." (PMID 37366674, 2023). "Multiple WNT genes have been identified as risk variants for cleft lip in humans, and knockout of Wnt9b in mice leads to cleft lip in part by reducing proliferation of the mesenchyme comprising the midface and preventing apposition of the facial primordia." (PMID 33855022, 2021). "An example in mice is the kidney defect and cleft lip syndrome caused by a null mutation at Wnt9b versus the non-syndromic cleft lip phenotype from a hypomorphic mutation at Wnt9b." (PMID 30134561, 2018). "Additionally, the A/Wsyn mouse, which also exhibits partial penetrance of cleft lip, appears to be caused by changes in methylation in genomic regions adjacent to Wnt9b." (PMID 33855022, 2021). "The importance of WNT9B regulatory function through classical WNT signaling pathway has been demonstrated in mice, where the disruption of WNT9B function has been associated with the formation of cleft lip and palate." (PMID 37366674, 2023). "Furthermore, knock-out of Wnt9b and Rspondin synergize to produce a more severe bilateral cleft lip." (PMID 33855022, 2021). "The biological interaction between WNT9B and PBX1 has been studied in cleft lip and/or palate resulting from abnormal morphogenesis of the face." (PMID 26075712, 2015).
MRKH syndrome (4 papers, 2015 to 2021). "Rs34072914 in WNT9B was found to be associated with MRKH syndrome (P = 0.024, OR = 2.65, 95%CI = 1.14–6.17)." (PMID 26075712, 2015). "The discovery of a four-gene epistatic effect (AMH, PBX1, WNT7A and WNT9B) in MRKH syndrome provides novel information for the elucidation of the genetic mechanism underlying the etiology of MRKH syndrome." (PMID 26075712, 2015). "Among the remaining 15 SNVs, rs34072914 in WNT9B was significantly associated with MRKH syndrome in this Chinese cohort (P = 0.026, OR = 2.575, 95%CI = 1.089–6.085)." (PMID 26075712, 2015). "The results obtained from our cohort suggest that rs34072914 interferes with the normal functioning of WNT9B and other related genes or pathways, perturbs MD development, causing the MRKH syndrome phenotype or multiple system malformations." (PMID 26075712, 2015). "However, a study of 542 Chinese patients excluded WNT9B as a causative gene for MDAs, although one study found a WNT9B polymorphism (rs34072914) to be highly associated with MRKH syndrome risk." (PMID 34160006, 2021). "However, in WNT4, which is associated with a distinct clinical entity of MRKH syndrome and signs of hyperandrogenism, and in its family member WNT9B, causative mutations have also been detected." (PMID 29527097, 2018). "All of these findings suggest a common pathway in MRKH syndrome with WNT9B acting upstream of WNT4 and LHX1." (PMID 29527097, 2018). "We observed significant additive interaction between the variants rs34072914 in WNT9B and rs2275558 in PBX1, which were each separately associated with MRKH syndrome risk in this cohort." (PMID 26075712, 2015). "The dominant models of rs34072914 and rs2275558 in WNT9B and PBX1, respectively, were significantly associated with MRKH syndrome risk in the Chinese Han patients." (PMID 26075712, 2015). "Multifactor dimensionality reduction (MDR) analysis revealed novel dimensional epistatic four-gene effects (AMH, PBX1, WNT7A and WNT9B) in MRKH syndrome." (PMID 26075712, 2015). "This association study successfully identified two susceptibility SNPs (WNT9B and PBX1) associated with MRKH syndrome risk, both separately and interactively." (PMID 26075712, 2015). "This study successfully identified two known SNPs (WNT9B and PBX1) that were separately and synergistically associated with MRKH syndrome and increased its risk in this case-control cohort." (PMID 26075712, 2015). "Notably, we found a novel dimensional epistatic four-gene effect (AMH, PBX1, WNT7A and WNT9B) in MRKH syndrome, providing novel data to contribute to the elucidation of the genetic mechanisms underlying its multifactorial etiology." (PMID 26075712, 2015). "The best four-way interaction model indicated by MDR analysis supported the following novel and bold assumption that the dimensional interactions of AMH, PBX1, WNT7A and WNT9B may play a role in the etiology of MRKH syndrome during MD development." (PMID 26075712, 2015).
breast carcinoma (3 papers, 2019 to 2025). "Therefore, in cases with ER-negative or low expression, Wnt9b still needs to be used in combination with other breast cancer markers to demonstrate its value in differential diagnosis." (PMID 40822238, 2025). "For the WNT9B protein (formerly WNT15), available data also report its involvement in some cancers, such as breast cancer, but not MM." (PMID 37239457, 2023).
cleft palate (3 papers, 2020 to 2023). Cleft palate is a fissure type embryopathy that affects the soft and hard palate to varying degrees. "Among them, WNT3 and WNT9B/Wnt9b mutations are associated with cleft palate/lip phenotype in humans and mice, respectively, suggesting that they are specific WNT ligands critical for facial development." (PMID 32457899, 2020). "Mice lacking the Wnt9b gene exhibited cleft lip with cleft palate, which resulted from a retarded outgrowth and subsequent failed fusion of the nasal processes (NP) and maxillary process of branchial arch 1 (MxBA1) due to significantly diminished WNT/β-catenin signaling." (PMID 32457899, 2020).
renal agenesis (3 papers, 2012 to 2024). Renal agenesis (RA) is a form of renal tract malformation characterized by the complete absence of development of one or both kidneys (unilateral RA or bilateral RA respectively), accompanied by absent ureter(s). "Wnt9b encodes a protein involved in MD development and Wnt9b knock-down in mice causes uterovaginal and renal agenesis." (PMID 38699388, 2024). "Wnt9b−/− embryos exhibit high penetrance cleft palate and renal agenesis phenotypes." (PMID 22912798, 2012).
cyst (2 papers, 2014 to 2022). A sac-like closed membranous structure that may be empty or contain fluid or amorphous material. "Mutations in the PCP-associated genes Wnt9b and Fat4 have been shown to lead to cyst formation in postnatal kidneys while other murine PCP gene mutations that are homozygous lethal, like Vangl2, show early hallmarks of cyst formation such as dilated tubules." (PMID 24852369, 2014).
orofacial cleft (2 papers, 2022 to 2023). A disorder of facial skeleton that is characterized by cleft lip and/or cleft palate that result in feeding, speech and hearing problems caused by failures during development. "Importantly, these four Wnt genes have been associated with human orofacial clefting, and alterations of Wnt9b also cause mouse CL/P." (PMID 35333176, 2022). "The main aim of this specific study is to assess the presence of SHH, SOX3, WNT3A and WNT9B proteins by immunohistochemistry within the non-syndromic cleft-affected epithelium and connective tissue in non-syndromic orofacial cleft patient groups together with a comparison with the control group." (PMID 37366674, 2023).
renal fibrosis (2 papers, 2014). A final common manifestation of a wide variety of chronic kidney diseases characterized by glomerulosclerosis and tubulointerstitial fibrosis. "All members of the WNT protein family (except WNT5b, WNT8b, and WNT9b), β-catenin, Dkk-1, FZD, fibronectin, and MMP-7 were upregulated in the UUO model of renal fibrosis." (PMID 24465439, 2014). "We speculated that Wnt2a, Wnt5b and Wnt9b might not participate in the formation of polycystic kidney lesions and renal fibrosis in the Gpr48 null mice." (PMID 24595031, 2014).
Aleutian disease (1 paper, 2024). "From this, we identified several candidate genes contributing to the growth and feed efficiency (ARID1B, APPL1, TOX, and GPC5), reproduction (GRM1, RNASE10, WNT3, WNT3A, and WNT9B), pelt quality (MYO10, and LIMS1), and Aleutian disease tests (IFNGR2, APEX1, UBE3A, and STX11)." (PMID 38167844, 2024).
apical periodontitis (1 paper, 2024). "“SNPs in WNT3, WNT3A, WNT5A, WNT8A, WNT9B, and WNT11 genes” were examined to check their association with apical periodontitis." (PMID 39723289, 2024).
coloboma (1 paper, 2018). An abnormality in which a part of a structure in one or both eyes is missing. "In examining the prioritized list of rare variants identified in superior coloboma patients, we note rare variants in NKD1, CELSR2, FZD4, SCRIB, and WNT9B (components of canonical or non-canonical Wnt pathways)." (PMID 29522511, 2018).
diabetes (1 paper, 2020). "Similarly, microarrays have been used to determine the key genes related to diabetes-associated impaired wound healing and have identified a range of relevant genes including the wnt family member 9B (Wnt9B), β-catenin, and transforming growth factor-β (TGF-β)." (PMID 32620711, 2020).
diabetic foot ulcers (1 paper, 2021). "Wnt9b may play a deleterious role in the development of diabetic foot ulcers, because inhibiting the canonical Wnt9b pathway by circulating exosomal miR‐20b‐5p from T2DM patients is found to suppress the angiogenenic effect of HUVECs in vitro and delay the wound healing in vivo." (PMID 34042263, 2021).
diabetic retinopathy (1 paper, 2023). "When investigating sub-phenotypes of T2DM, diabetic retinopathy has been identified to be associated with ACVRIC (rs4664229), ZFHX4 (rs61729527), WNT9B (rs4968281), SHANK3 (rs9616915), ZSCAN5A (rs7252603), and DCP1B (rs715146, rs1044950, rs113147414) gene." (PMID 37033211, 2023). "The association with pulse pressure and blood pressure have been associated to diabetic retinopathy through arterial stiffness and vision impairment, which has been identified in multiple genes, including the ZFHX4 gene, the SHANK3 gene, and the WNT9B gene." (PMID 37033211, 2023).
Gorlin syndrome (1 paper, 2017). "Thus, mutations in FAT4 and WNT9b may also play a supporting role in the development of Gorlin syndrome." (PMID 28915250, 2017).
Kidney Cyst (1 paper, 2012). Abnormal fluid filled sac within the kidney, either acquired or congenital. "Wnt9b transgene activation in Six2-positive cells causes kidney cysts and a transformation of the distal stomach regions into proximal stomach fate." (PMID 22912798, 2012). "The presence of kidney cysts in Wnt9b transgenic animals strengthens the conclusion that disruption of the Wnt signaling system causes cystic disease." (PMID 22912798, 2012). "Persistent expression of Wnt9b in Six2-positive cells leads to kidney cysts and severe organ failure." (PMID 22912798, 2012).
leiomyosarcoma (1 paper, 2018). An uncommon, aggressive malignant smooth muscle neoplasm, usually occurring in post-menopausal women. "WNT9B (17q21.32), S phase entry blocker growth arrest specific 1 (GAS1) and serine/threonine protein kinase D1 (PRKD1) were expressed at low levels in PTSMT while the other analyzed tumor types showed higher levels, in particular, leiomyosarcomas." (PMID 29881541, 2018).
lung carcinoma (1 paper, 2022). "According to recent publications, WNT9B, as the multi-omics biomarker for lung cancer at both epigenomics and genomics levels has been shown to act as an effective drug target." (PMID 35155435, 2022).
multiple sclerosis (1 paper, 2025). A progressive autoimmune disorder affecting the central nervous system resulting in demyelination. "The predicted target gene WNT9B by circFECH was found with genetic variations in multiple sclerosis, which is also a neuronal disorder." (PMID 41327336, 2025).
osteoporosis (1 paper, 2015). A condition of reduced bone mass, with decreased cortical thickness and a decrease in the number and size of the trabeculae of cancellous bone (but normal chemical composition), resulting in increased fracture incidence. "The evidence taken together supported the importance of WNT3 and WNT9B in the Wnt signaling pathway in determining osteoporosis." (PMID 25811989, 2015).
prostatic intraepithelial neoplasia (1 paper, 2015). "This was observed in a mouse model of prostatic intraepithelial neoplasia, where overexpression of Hmga2 in cancer-associated fibroblasts enhances expression of the Wnt ligands Wnt2, Wnt4, and Wnt9b, concomitant with enhanced Wnt signaling and nuclear β-catenin in adjacent neoplastic epithelium." (PMID 26244988, 2015).
renal failure (1 paper, 2012). "In contrast, expression of Wnt9b in cells using Six2-cre caused gastrointestinal distress and severe renal failure in adult mice." (PMID 22912798, 2012).
septal defects (1 paper, 2024). "In the eQTL analysis the variants rs2316327 (general CHD), and rs75230966 (septal defects) both located in 17q21.32 (with a LD r2 of 0.41) were both predicted to significantly associate with the expression of WNT9B in the atrial appendage tissue category." (PMID 38454350, 2024).
Stroke (1 paper, 2023). Sudden impairment of blood flow to a part of the brain due to occlusion or rupture of an artery to the brain. "A total of five significantly DE genes were identified at pre-stroke, including three upregulated (Cyp2a5, Wnt9b, Gfy) and two (Prl, Gh) downregulated genes." (PMID 37175797, 2023). "We identified Il-1β, Ccl2, Cybb, Wnt9b, as well as some pathway-specific genes such as S100a8 and S100a9 (IL-17 signaling) among the common pro-inflammatory and signaling molecules whose expression was affected by higher TMAO levels in post-stroke animals." (PMID 37175797, 2023).
virus infection (1 paper, 2013). "WNT2B and WNT9B secretion in response to viral infection induce a CTNNB1-dependent signaling pathway leading to decreased magnitude of IFNB1 production and effector response in a feedback inhibition mechanism." (PMID 23785285, 2013). "Here we show that secretion of WNT2B and WNT9B and stabilization of β-catenin (CTNNB1) upon virus infection negatively regulate expression of representative inducible genes IFNB1, IFIT1 and TNF in a CTNNB1-dependent effector mechanism." (PMID 23785285, 2013).
tumor (9 papers, 2018 to 2025). "In contrast, the consistent hypermethylation at CpG islands associated with genes such as HNF1β, PAX2, SOX9 and WNT9B implies that epigenetic control of nephrogenesis is dysregulated in a targeted fashion in Subgroup B tumours." (PMID 33012783, 2021). "For PFS cytoplasmatic WNT9B was found to be associated with better patient survival in the tumour cells (p = 0.029) as well as in the stroma (p = 0.017), which was confirmed (HR 0.67, 95% CI 0.48–0.92, p = 0.014) by multivariate analysis for the expression in the TME." (PMID 38361045, 2024). "Antibody staining was detected in both primary and recurrent tumours and was mainly located in the cytoplasmic cell compartment with only WNT9B showing additional nuclear and ITGA5 showing sporadic membranous staining." (PMID 38361045, 2024). "Expression levels the remaining Wnt ligands, including Wnt1, Wnt3, Wnt4, Wnt5A, Wnt8A, Wnt9B, Wnt10A and Wnt16, remained insignificantly different between liver tumors tissues and adjacent non-tumor tissues." (PMID 30814912, 2019). "The results of WNTs’ mRNA level assessment in the MSCs of the tumor niche in MM suggest possible prospects for mRNAs of WNT2B, WNT9B and CTNNB1 as being molecular prognostic markers that can predict the outcome of the disease." (PMID 37239457, 2023). "A heatmap of the 110 CpGs shows overall lower methylation of these CpGs in tumors compared to adjacent non-tumor tissues: the top five hypermethylated genes were GLRX, WNT9B, SEPT9, KIAA00284, and PPYR1, and the top five hypomethylated genes were KIAA0748, PAEP, PCDH15, PTPRN2, and DUSP27." (PMID 34635168, 2021).
cancer (6 papers, 2015 to 2025). A tumor composed of atypical neoplastic, often pleomorphic cells that invade other tissues. "ACTG1, SDC1, FRS2, and WNT9B were commonly identified as genes contributing to the enrichment of the ‘Proteoglycans in Cancer’ pathway in both species." (PMID 41296454, 2025). "However, little is known about the role of Wnt9b in tumorigenesis, and only one study indirectly reported that the expression of Wnt9b was downregulated by a cancer-preventing glycoconjugate in CRC cells, indicating a potential carcinogenic property of Wnt9b." (PMID 32923386, 2020). "Target prediction and functional annotation identified 59 overlapping genes, with the Proteoglycans in cancer pathways being conserved in both species, mediated by ACTG1, SDC1, FRS2, and WNT9B." (PMID 41296454, 2025). "Notably, only one pathway, Proteoglycans in cancer (p < 0.05), was conserved across both species, with ACTG1, SDC1, FRS2, and WNT9B identified as common genes participating in this pathway." (PMID 41296454, 2025).
WNT9B also shares sentences with these, for which no sentence is quoted: Mayer-Rokitansky-Küster-Hauser Syndrome (2 papers); Alagille syndrome (1); basal cell carcinoma (1); CATSHL syndrome (1); cholestasis (1); Ellis-van Creveld syndrome (1); Fraser syndrome (1); heart defects (1); hyperandrogenism (1); Hypergonadotropic hypogonadism (1); infection (1); lymphoma (1); Noonan syndrome (1); Obesity (1); Primary amenorrhea (1); psychiatric disorder (1); type 2 diabetes mellitus (1).